TLR4 (toll like receptor 4)
Diseases named in the same sentence as TLR4 in open-access papers (continued):
Sharing a sentence is not in itself a finding about the gene and the disease.
Sepsis (continued). "TLR4 is another critical player in sepsis-induced liver injury." (PMID 39067063, 2025). "Despite the ineffectiveness of TLR4 antagonists, like eritoran, to successfully prevent acute sepsis, the discovery of TLR4 modulators as prospective therapeutics for chronic inflammatory disorders whose pathophysiology appears to involve TLR4 remains an active area." (PMID 40649397, 2025). "Relevant experimental studies on septic myocardial dysfunction indicate that simvastatin may mitigate the inflammatory response in the hearts of rats with sepsis-induced myocardial depression by inhibiting the TLR4-NFκB pathway." (PMID 40176909, 2025). "In a related study, another research group explored the potential of multifunctional biomimetic liposomes incorporating a novel TLR4‐targeting peptide designed to modulate the inflammatory response while simultaneously enhancing the delivery of vancomycin against sepsis." (PMID 40599085, 2025). "The findings suggest that APS nanoparticles could protect against sepsis‐induced cardiac dysfunction by modulating the TLR4/NF‐κB pathway." (PMID 40599085, 2025). "Furthermore, TLR4/NF-κB pathway inhibition also ameliorates sepsis-induced cardiac dysfunction in rats." (PMID 40640887, 2025). "Notably, the synthetic lipid TLR4 antagonist Eritoran has demonstrated the ability in preclinical studies to attenuate LPS-induced inflammation and improve survival rates in sepsis models." (PMID 41041277, 2025). "Thus, the activation of both TLR2 and TLR4 is expected to play a critical role in the pathogenesis of sepsis." (PMID 40963927, 2025). "to directly target toll-like receptor 4 (TLR4) to regulate immunity in sepsis." (PMID 39958360, 2025). "TLR4 mRNA expression was also significantly increased following sepsis induction." (PMID 40869248, 2025). "These multiple lines of evidence indicate that simultaneous inhibition of TLR2 and TLR4 activation may serve as a promising therapeutic strategy for controlling overwhelming inflammation in sepsis." (PMID 40963927, 2025). "The TLR4 agonist LPS was limited in early clinical trials due to inducing sepsis-like reactions." (PMID 41568029, 2025). "Docking simulations may also reveal novel multi-target inhibitors—for example, a single polyphenol capable of simultaneously blocking TLR4 dimerization and caspase-3 activation-addressing sepsis heterogeneity more effectively than single-pathway drugs." (PMID 40509176, 2025). "In a sepsis study, murine and pig models were treated with the novel tripeptide Arg-Lys-His derived from A. muciniphila, which was reported to reduce inflammation symptoms through TLR4 inhibition." (PMID 39940420, 2025). "Moreover, MMF potentially attenuates sepsis-induced liver dysfunction by inhibiting the TLR-4/NF-κB signaling pathway." (PMID 40386784, 2025). "In sepsis, the LPS-induced activation of the TLR4-NF-κB axis drives the cytokine storm." (PMID 41411324, 2025). "Further, we found the expression level of TLR4 on monocytes in heatstroke was higher than that in sepsis and could differentiate the diagnosis of heatstroke from sepsis, which wasn't found in previous study." (PMID 40084252, 2025). "24h after sepsis induction, the expression of Tlr4 was also upregulated in CLP." (PMID 40253667, 2025). "Thus, we tested the anti‐inflammatory potential of TDIPs by inhibition of TLR4 in a mouse sepsis model." (PMID 39482884, 2025). "TLR4 also interacts with CD14, damage-associated molecular patterns (e.g., HMGB1), and NETs, amplifying inflammatory and coagulation pathways that link thrombocytopenia and sepsis progression." (PMID 40003683, 2025). "However, in sepsis models, sevoflurane interferes with the formation of the TLR4-MD-2-LPS complex in a dose-dependent manner, inhibits TLR4 activation, attenuates NF-κB signaling, and exerts anti-inflammatory effects." (PMID 40896344, 2025).
Sepsis (continued). "Differential activation of these receptors—for example, TLR4 in sepsis or TLR7 in viral infections—may serve as a cellular signature of pathogen type." (PMID 40692784, 2025). "However, sepsis represents a highly complex condition involving dysregulation of the immune system, with TLR-4 being only one component of an extensive network of inflammatory mediators." (PMID 40404908, 2025). "Second, these morphine effects appear to be mediated via the μ-opioid receptor and driven by the intensified inflammatory response to sepsis as suggested by the augmented expression of the inflammatory TLR4 and chemotactic MCP1 signals in peripheral (heart) and brainstem (RVLM) sites." (PMID 40573276, 2025). "Similarly, in a rat model of sepsis, TLR4 activation by LPS in cardiomyocytes promotes mitochondrial ROS production, oxidation of RyR2 and SR Ca2+ leak." (PMID 40649397, 2025). "Accumulating evidence suggests that the cross-talking of JAK2/STAT3 (p-JAK2 and phospho-Tyr705) with other pathways such as NF-κB (p-IKKα/β, p-IκBα and p-P65), MAPK (p-JNK, pJun, p-P38 and p-ERK1/2), AKT (p-AKT), TLR4, mediate hyperinflammatory factor production during sepsis." (PMID 41042728, 2025). "However, in sepsis, the excessive activation of TLR4 results in impaired LSEC function, increased endothelial barrier permeability, and exacerbated endotoxin circulation and multi-organ dysfunction." (PMID 40072101, 2025). "By binding to TLR4, LPS triggers a series of cascade reactions, inducing host immune cells to release many inflammatory factors, thus driving the pathological progression of sepsis." (PMID 41041277, 2025). "Therefore, interference with the TLR4 signaling pathway has been proposed as a potential therapeutic target to decrease inflammation and sepsis-induced AKI." (PMID 40869248, 2025). "TLR4 involvement is highly context-dependent, being enhanced in inflammatory states including sepsis or metabolic syndrome but minimal under baseline conditions, and discrepant results in TLR4-knockout models suggest contributions from co-receptors or alternative pathways." (PMID 41347124, 2025). "As a critical PRR in sepsis, TLR4 recognizes several DAMPs, such as eCIRP, HMGB1, and histones." (PMID 40421030, 2025). "Panax ginseng and its active ginsenosides (e.g., Rg1) have been shown to alleviate intestinal barrier disruption and suppress pro-inflammatory cytokines in CLP-induced sepsis, potentially through inhibition of the TLR4/NF-κB pathway, leading to reduced IL-6 and TNF-α levels." (PMID 41357500, 2025). "Our finding that morphine augmented the sepsis-evoked rises in cardiac/RVLM expression of TLR4 and MCP1 indicate that peripheral and central pathways of these signaling molecules contribute the deteriorated cardiovascular profile of morphine-treated septic rats." (PMID 40573276, 2025). "However, overactivation of TLR4-mediated inflammation by lipopolysaccharide (LPS) can lead to detrimental outcomes such as sepsis, acute lung injury, and chronic inflammation, often associated with cancer and autoimmune diseases." (PMID 39294631, 2024). "Numerous studies have suggested that TLR4 is a “double-edged sword” during sepsis." (PMID 38549133, 2024). "Overall, these findings indicated that CBP can promote TLR4-TIR acetylation, while HDAC1 may also serve as the deacetylase of TLR4-TIR in human CD16+ monocytes during sepsis." (PMID 39294473, 2024). "Therefore, sphinganine biosynthesis is required for the initiation of TLR4 signal transduction and serves as a checkpoint for macrophage pattern recognition in sepsis and melanoma mouse models." (PMID 39025856, 2024). "-Let-7a acts as a TLR4 antagonist.-Let-7a is correlated with reduced TNF alpha, interleukin1β, and TLR signaling in an LPS-induced manner.-Levels of let-7a is associated with the regulation of the TLR-mediated immune response in sepsis." (PMID 38756232, 2024).
Sepsis (continued). "We observed that resveratrol, both in its native form and encapsulated within silver nanoparticles, could substantially mitigate the sepsis-induced changes in the expression of Bcl-2, Caspase-3, TLR4, IL-1Β, and TNF-α." (PMID 38546748, 2024). "For instance, papiliocin, an insect cecropin recognized as an anti-endotoxin AMP, alleviates the impact of E. coli-induced sepsis and exhibits immunomodulatory effects by inhibiting the TLR4-NFκB signaling pathway through competitive interference with the LPS-TLR4/MD-2 interaction." (PMID 39596204, 2024). "Recent research underscores the critical role of TLR4 in autophagy regulation during sepsis." (PMID 39544947, 2024). "However, in a pig model of trauma and delayed sepsis, LPS-induced TLR4 signaling leads to a significant reduction in endogenous DHEA levels." (PMID 38792602, 2024). "Identified in 1999 as a late-stage mediator of sepsis, HMGB1 acts as a damage-associated molecular pattern (DAMP), prolonging inflammation by activating macrophages via Toll-like receptor 4 (TLR4) and the receptor for Advanced Glycation Endproduct (RAGE) pathways." (PMID 39201697, 2024). "Another study revealed that naringenin protects against sepsis-related lung damage through AMPK-activating transcription factor 3 (ATF3)-dependent negative regulation of the LPS/TLR4 signaling pathway, suppressing the expression of TNF-α, IL-6, TLR4, iNOS, cyclo-oxygenase-2 (COX2), and NOX2." (PMID 39126050, 2024). "Therefore, as a crucial regulation molecule of endotoxemia or sepsis, TLR4 expression on the cell membrane surface is tightly regulated." (PMID 38549133, 2024). "Notably, the TLR4 antagonist E5564 (eritoran) showed toleration in phase II clinical trials for sepsis treatment." (PMID 38790263, 2024). "Similarly, we further validated the protective effect of Cmtm3 knockout through the TLR4 pathway in a CLP-induced sepsis model." (PMID 39455728, 2024). "TLR4 plays a critical role in coordinating the immuno-inflammatory response during sepsis." (PMID 38549133, 2024). "Low expression of ARHGEF10L in CD14 + monocytes is associated with increased death from sepsis, and the list included genes related to anti-bacterial activity (LCN2), regulation of TLR4 responses (SLC15A3), LPS sensitivity and autophagy (RUBCNL and SLC8A1) and apoptosis (FAS, TNFRSF21, TNFRSF8)." (PMID 39730996, 2024). "A. muciniphila derived tripeptide RKH could suppress the expression of proinflammatory cytokines in macrophages after LPS stimulation and directly bind to TLR4 and inhibit systemic inflammation of sepsis." (PMID 38384263, 2024). "The TLR4 signaling cascade that increases EC permeability involves dysregulated activity of a mechanosensitive ion channel protein, Piezo1, and NOX4, a key ROS-producing target implicated in the pathogenesis of both sepsis and ARDS." (PMID 38345908, 2024). "Our findings highlight the important role of TLR4-TIR domain acetylation in the regulation of the immune responses in sepsis, and we propose this reversible acetylation of TLR4 signalosomes as a potential therapeutic target for M1 macrophages during the progression of sepsis." (PMID 39294473, 2024). "Previous studies have reported that TLR4 mediates sepsis-induced liver damage through the ISR42." (PMID 38316963, 2024). "Further evidence for a central role of TLR4 in the development of sepsis." (PMID 39720715, 2024). "TLR4 is dispensable for this response, as demonstrated in TLR4-deficient mice, which were primed with a TLR3 agonist to activate caspase 11 and were as susceptible to LPS-triggered sepsis as wildtype animals." (PMID 38671891, 2024). "In addition, future research should focus on elucidating the precise molecular mechanisms by which CMTM3 regulates TLR4 expression, to clarify its dual role in sepsis." (PMID 39455728, 2024).
Sepsis (continued). "In addition, TLR4-TIR acetylation of PBMCs enriched monocytes from normal individuals and sepsis patients was analyzed by flow cytometry using specific TLR4-acK732 and TLR4-acK813 antibodies." (PMID 39294473, 2024). "Notably, in the sepsis patients, TLR4-TIR acetylation was predominantly observed in CD16+ monocytes combined with elevated expression of M1 macrophage markers." (PMID 39294473, 2024). "TLR2 and TLR4 mRNA upregulation is also described in monocytes from patients with sepsis." (PMID 38835761, 2024). "Additionally, silenced C5ar1 inhibited the TLR2, TLR4, and peptidylarginine deiminase 4 expression levels, which suggested the improvement of silenced C5ar1 on sepsis via inhibiting NETs and the TLR signaling pathway." (PMID 38165570, 2024). "Collectively, TLR4 is able to amplify the inflammatory cascade at the early stage of sepsis." (PMID 38159178, 2024). "Overexpression of miR-22 could target and suppress the expression of HMGB1, inhibit the release of inflammatory factors and the expression of HMGB1/TLR4/NF-κB signaling pathway-related proteins, to attenuate the sepsis-induced AKI." (PMID 35960478, 2023). "In sepsis, trials are in progress to test TLR4 antagonists (Clinical Trial # NCT00334828)." (PMID 36703865, 2023). "It has been reported that sepsis is related to the activation of TLR4." (PMID 38102579, 2023). "Recent research found that miRNA could regulate the TLR4/NFκB pathway, a pathway responsible for the expression of pro-inflammatory cytokines in sepsis." (PMID 36855106, 2023). "Taken together, these findings demonstrated that sepsis activated platelets via TLR4, and that further platelet secretion was controlled by IKK activity, which could become a therapeutic target for managing septic AKI." (PMID 37928258, 2023). "Indeed, using the cecal ligation and puncture (CLP) sepsis model, TLR4 activation increased TNF-α serum levels as early as 4 h after surgery." (PMID 37600769, 2023). "Moreover, MCP-1 provokes systemic inflammation following TLR-4 activation and is readily elevated in animal models of sepsis." (PMID 37180728, 2023). "In addition, the activation of TLR4-mediated NF-κB signaling pathway was suggested to be positively correlated to inflammation and apoptosis during sepsis induced organ dysfunction." (PMID 37650558, 2023). "Limited evidence suggests that toll-like receptor 4 (TLR-4) formation and platelet-leukocyte aggregates (PLA) may be associated with the development of sepsis-associated thrombocytopenia." (PMID 37841241, 2023). "For example, since TLR4 induces excessive inflammation in sepsis, antagonists targeting TLR4 have been used in a phase II clinical trial that aims to decrease the mortality of patients with sepsis." (PMID 36749634, 2023). "Thus, it can be concluded that MAF as a treatment reduces the inflammatory responses in vitro and in vivo by inhibiting the TLR4/ MyD88/NF‐κB pathway, and corrects intestinal flora imbalance during sepsis to some degree." (PMID 38455195, 2023). "In addition, multiple inflammation-related receptors, such as TLR4 and integrin subunit α M (Itgam, also called Cd11b) were induced in PBMCs from patients with sepsis." (PMID 36749634, 2023). "Moreover, the prominent regulatory role of TLR4 has also been explored in the LPS-mediated endotoxin shock and sepsis model in mice using TAK-242 as a probable TLR4 antagonist." (PMID 37153546, 2023). "Note that, although the expression of CASP11 induced by LPS requires TLR4, it is not necessary for sepsis death induced by poly(I:C), which may help explain the unsatisfactory results of clinical trials attempting to treat sepsis with TLR4 inhibitors." (PMID 38020710, 2023). "For example, NEAT1 was reported to promote the inflammatory response by regulating the Let‐7a/TLR4 axis in sepsis‐induced liver injury, whereas silencing the lncRNA XIST protected against sepsis‐induced acute liver injury through the inhibition of bromodomain‐containing protein 4 expression." (PMID 37829506, 2023).
Sepsis (continued). "It is not understood why viral infections can also cause sepsis although viruses do not express ligands for TLR-4 or TLR-2, the prototypic TLRs involved in bacterial sepsis and septic shock." (PMID 36851312, 2023). "PB2 may protect the lung tissue from LPS-induced injuries by inhibiting the cytokine storm of sepsis through downregulating TLR4/NF-κB and upregulating PI3K/Akt." (PMID 37175637, 2023). "As a result, it is crucial to emphasize the potential molecular mechanisms of the TLR4/IKKα-mediated NF-κB signaling pathway that may be involved in the inflammatory response and apoptosis during the pathophysiology of sepsis." (PMID 37650558, 2023). "Finally, although we interrogated the potential role of Paquinimod in ameliorating sepsis-induced immunosuppression, its effect on TLR4 in the bone marrow requires to be explored." (PMID 37337301, 2023). "Therefore, new therapeutic molecules have been developed to prevent uncontrolled bacterial endotoxin-mediated sepsis by targeting the LPS-stimulated TLR4 signaling pathway to develop new antagonists by targeting TLR4 and MD-2." (PMID 37958587, 2023). "An example is TAK 242 (resatorvid), a small-molecule inhibitor of TLR4 signaling, initially developed as an anti-sepsis agent specifically disrupting the TLR4-TIRAP interaction with high selectivity and capable of inhibiting inflammatory mediator production at nanomolar levels." (PMID 37773180, 2023). "Thus, our findings suggested that anti–pCTS-L pAbs conferred protection against lethal sepsis partly by attenuating pCTS-L–induced dysregulated inflammation orchestrated by both TLR4 and RAGE receptors." (PMID 36735789, 2023). "In the study, mimics miR-22 could remarkably downregulate the LPS-induced increased TLR4, TLR2, MyD88, and p-NF-κB p65 protein expression, which indicated that miR-22 may alleviate sepsis-induced AKI by targeting HMGB1/TLR4/NF-κB signaling pathway." (PMID 35960478, 2023). "DMB rescued mice from sepsis shock induced by LPS through targeting the TLR4–MD-2 complex." (PMID 37168866, 2023). "However, TLR4 agonists can significantly increase the expression of TLR4/MyD88/NF-κB signalling, thus reversing the protective effect of ulinastatin on sepsis." (PMID 38102579, 2023). "All of those indicated that miR-22 could alleviate sepsis-related AKI via targeting the HMGB1/TLR4/NF-κB signaling pathway." (PMID 35960478, 2023). "However, the development of therapies that are capable of controlling TLR4-mediated inflammation has stalled following the failure of the antisepsis drug candidate Eritoran to improve survival in sepsis patients in a Phase 3 clinical trial." (PMID 37630200, 2023). "Due to septic patients’ complicated and varied immunological status, TLR4 inhibitors may benefit patients early in the sepsis’ inflammatory phase or in combination with other medicines." (PMID 38114466, 2023). "As a PRP, TLR4 is activated by LPS and regulates inflammatory process and cell death during sepsis." (PMID 37928258, 2023). "Finally, the efficacy and pharmacological mechanisms of XBJ for the treatment of sepsis have been demonstrated, with the anti-inflammatory effects of XBJ on sepsis through targeting the TLR4/NF-κB signaling pathway being particularly well elaborated." (PMID 37650558, 2023). "Therefore, this study posits that within sepsis-induced acute liver injury, PICK1 potentially exerts a protective role on the liver by associating with TLR4 to inhibit the release of inflammatory factors and hepatocyte apoptosis." (PMID 37488153, 2023). "In addition, a bioinformatic study found that TLR4 was screened out as one of the hub genes enriched in the ferroptosis pathway in child sepsis." (PMID 36837498, 2023). "In part, the TLR4-independent LPS sensing mechanism may be more important in the development of sepsis than the TLR4-dependent LPS sensing mechanism." (PMID 37700349, 2023).